CDC42 (cell division cycle 42)
Diseases named in the same sentence as CDC42 in open-access papers (continued):
Sharing a sentence is not in itself a finding about the gene and the disease.
renal fibrosis (3 papers, 2023 to 2024). A final common manifestation of a wide variety of chronic kidney diseases characterized by glomerulosclerosis and tubulointerstitial fibrosis. "Cdc42 is known to initiate p-PKCζ/pGSK3β signaling, which is involved in renal fibrosis by inhibiting p-β-catenin and upregulating β-catenin." (PMID 39559701, 2024). "CDC42 has also been suggested as a therapeutic target for renal fibrosis induced by TGF-β." (PMID 39480826, 2024). "The core genes SRC, IGF1, RHOA, ESR1, EGFR and CDC42 may play a key role in the inhibition of the development and progression of renal fibrosis by diosgenin." (PMID 37179298, 2023). "Research indicated that ARAP1‐AS2/ARAP1 may participate in cytoskeleton rearrangement and EMT processes in HK‐2 cells through increased CDC42-GTP levels and induced renal Fibrosis." (PMID 37179298, 2023).
rheumatoid arthritis (3 papers, 2018 to 2022). A chronic, systemic autoimmune disorder characterized by inflammation in the synovial membranes and articular surfaces. "PAK1, a potential mediator of Rac1/Cdc42 signaling pathway, is involved in regulating the migration, invasion, proliferation, and inflammation of fibroblast-like synoviocytes from rheumatoid arthritis patients." (PMID 33482886, 2021).
22q11.2 deletion syndrome (2 papers, 2021). 22q11.2 deletion syndrome (DS) is a chromosomal anomaly which causes a congenital malformation disorder whose common features include cardiac defects, palatal anomalies, facial dysmorphism, developmental delay and immune deficiency. "The expression of constitutively active Cdc42 increased spine density in cultured hippocampal neurons and rescued the spine density deficit in LgDel mice, a model for 22q11.2 deletion syndrome with altered Cdc42 signaling." (PMID 34671600, 2021).
Actinopathies (2 papers, 2024 to 2025). "Defects in both CDC42 and RAC2 GTPases have been linked with actinopathies but associated with distinct immune disorders." (PMID 40860338, 2025). "Majority of patients from MENA-IEI registry with actinopathies have defects in CDC42 GTPase and RAC2 GTPase pathways." (PMID 40860338, 2025). "Actinopathies, including DOCK8, WASP and CDC42 deficiencies, are associated with migration defects of various immune cells." (PMID 39120629, 2024). "Although we did not observe a clear genotype-phenotype correlation between patients with different types of actinopathies, specific genetic defects mainly from the CDC42 GTPase pathway including WAS and DOCK8 showed higher mortality in the context of severe genetic mutations." (PMID 40860338, 2025). "A literature review of actine-related IEIs showed that only diseases affecting the CDC42 GTPase pathway, namely WAS and DOCK8, have been reported in large enough numbers to allow a comparative analysis of different actinopathies." (PMID 40860338, 2025).
acute lung injury (2 papers, 2018 to 2024). A condition of lung damage that is characterized by bilateral pulmonary infiltrates (pulmonary edema) rich in neutrophils, and in the absence of clinical heart failure. "In vivo, we just performed some preliminary phenotypic evaluations to assess the role of CDC42-165aa in a KP-induced acute lung injury mouse model." (PMID 38977695, 2024). "In LPS-induced acute lung injury (ALI) mouse models, knockout of the Cdc42 gene in ECs increased inflammatory cell infiltration and pulmonary vascular leakage and inhibited vascular EC proliferation, which eventually resulted in more severe inflammatory lung injury." (PMID 29422044, 2018).
acute pancreatitis (2 papers, 2020 to 2025). An acute inflammatory process that leads to necrosis of the pancreatic parenchyma. "Other studies demonstrated that the inhibition of Ras signaling decreased the severity of taurocholate induced acute pancreatitis and that the ameliorating effect of the flavone, baicalin, on acute pancreatitis was due in part to its inhibition of Cdc42." (PMID 40001881, 2025). "The studies above providing evidence that the activation of PAKs may play an important role in acute pancreatitis are supported by studies reporting important roles for Ras, Rac and Cdc42 activation in acute pancreatitis." (PMID 40001881, 2025). "The present study aimed to investigate the effect of carbachol on the intestinal tight-junction barrier in a rat model of severe acute pancreatitis (SAP) without aggravating pancreatic injury, and to determine whether cell division cycle 42 (Cdc42)/F-actin could have a regulatory role." (PMID 32765779, 2020).
anaplastic large cell lymphoma (2 papers, 2009 to 2015). Anaplastic large cell lymphoma (ALCL) is a rare and aggressive peripheral T-cell non-Hodgkin lymphoma, belonging to the group of CD30-positive lymphoproliferative disorders, which affects lymph nodes and extranodal sites. "In future investigation Rac1 and Cdc42, which are members of cell motility-regulating proteins will be analyzed in galectin-8-mediated cell invasion in anaplastic large cell lymphoma." (PMID 25573487, 2015). "It is worth mentioning that it has been observed that CDC42 controls the cell growth of anaplastic large cell lymphoma through its activation." (PMID 20015360, 2009).
anemia (2 papers, 2020 to 2023). A reduction in the number of red blood cells, the amount of hemoglobin, and/or the volume of packed red blood cells. "However, to the best of our knowledge, erythrocytic anomalies, such as anemia, attributed to Cdc42 abnormalities have not yet been reported." (PMID 32678227, 2020).
Arthritis (2 papers, 2019 to 2021). Inflammation of a joint. "Here we show that heterozygous deletion of the Rho family gene Rac1, but not Rhoa and Cdc42, reverses inflammation and arthritis in GGTase-I-deficient mice." (PMID 31484924, 2019). "However, only heterozygous deletion of gene Rac1, but not Cdc42 and RhoA, could reverse inflammation in mouse models for arthritis, indicating the special role of Rac1 in chronic inflammation diseases." (PMID 34805177, 2021).
astrocytoma (2 papers, 2013 to 2019). "Moreover, Ect2 co-localizes with Rac1 and Cdc42 in the membrane ruffles of migratory astrocytoma cells, and inhibition of Ect2 led to decreased Rac1 and Cdc42 activity, with no change in Rho activity." (PMID 24109588, 2013). "In a previous study from our laboratory, we observed an increase in ERK phosphorylation in response to STARD13 knockdown in astrocytoma cells, also placing ERK downstream from CDC42." (PMID 30781697, 2019).
brain injury (2 papers, 2019 to 2023). Acute and chronic (see also brain INJURIES, CHRONIC) injuries to the brain, including the cerebral hemispheres, CEREBELLUM, and brain STEM. "In short, the present study indicates that SVCT2 promotes NSPCs migration through CDC42 activation to facilitate F-actin assembling, which enlarges the therapeutic scope of AA and the role of SVCT2 in NSPCs migration after brain injury." (PMID 31607868, 2019). "Collectively, the present study indicates that SVCT2 promotes NSPCs migration through CDC42 activation to facilitate F-actin assembling, which enlarges the therapeutic scope of AA and the role of SVCT2 in NSPCs migration after brain injury." (PMID 31607868, 2019). "Another study found that functional recovery was improved with ascorbic acid and sodium–vitamin C cotransporter 2 promoted NSCs’ migration through Cdc42 activation to facilitate F-actin assembly, which increased the therapeutic effect of ascorbic acid and NSC migration after brain injury." (PMID 36975497, 2023).
Cerebral ischemia (2 papers, 2020 to 2023). Restriction of arterial blood supply to the brain associated with insufficient oxygenation to support the metabolic requirements of the tissue. "By causing Cdc42 succinylation, ischemic buildup of succinate lowers the activity of Cdc42 GTPase, which reduces the proliferation of neural stem cells and exacerbates cerebral ischemia/reperfusion injury." (PMID 36975497, 2023). "Further, axon repair and nerve regeneration were promoted after cerebral ischemia through Netrin-1/Rac1/Cdc42 signalling pathways." (PMID 36975497, 2023).
ciliopathy (2 papers, 2022). A genetic disorder of the cellular cilia or the cilia anchoring structures, the basal bodies, or of ciliary function. "Mutations in OCRL could therefore cause its ciliopathy by an increase in PIP2, by overactivity of Rac1 and Cdc42, and by impaired endocytosis (impaired endocytosis may trigger ciliary shortening by causing agonist-induced vesicle budding)." (PMID 35079141, 2022).
colitis (2 papers, 2021 to 2024). Inflammation of the colon. "In the context of mouse experimental colitis, overexpression of CDC42 through injection of corresponding adenovirus vector, resulted in reduced levels of the cytokines IL-10, IFN-γ, IL-4, and TNF in TNBS-treated mice." (PMID 33406731, 2021). "A recent publication describes the mechanism by which HuR (RNA-binding protein HuR) promotes protein expression of CDC42 within IECs, contributing to epithelial restitution (healing) in ischemia as well as colitis models (DSS), in a mechanism that is dependent on the actin cytoskeleton." (PMID 33406731, 2021). "Using a different Cre-deleter, it was shown that mice lacking CDC42 in T cells (Cdc42-LCKCre) have enhanced Th17 differentiation and suffer from a wasting disease in mouse models of colitis, causing a fatal lymphoproliferative disease." (PMID 33406731, 2021). "miR-21 KO mice are protected against DSS-induced colitis by simultaneously promoting RHOB and decreasing CDC42 expression, therefore improving epithelial integrity." (PMID 33406731, 2021).
colon adenocarcinoma (2 papers, 2011 to 2017). "In parallel, KRASG12V enhances the ability of colon adenocarcinoma cells Caco-2 to migrate and invade through filopodia formation and PI3K-dependent Cdc42 activation." (PMID 21943101, 2011).
congenital heart defects (2 papers, 2019 to 2024). "Interestingly in humans, pathogenic variants in both RAC1 and CDC42 have been associated with malformation syndromes, including congenital heart defects." (PMID 38501224, 2024). "Among these genes, AKT1, PDPK1, CDC42, AKT3, and PIK3CA have concrete evidences shown in relation with congenital heart disease; even two of them (AKT1, CDC42) have explicit association with VSD." (PMID 31440271, 2019).
demyelinating disease (2 papers, 2014 to 2022). A broad group of disorders that affect the myelin sheaths that cover the neurons. "In a study of an early onset demyelinating disease, classified as CMT4H in one Lebanese and one Algerian family, Delague and colleagues identified novel mutations in a protein directly influencing the activity of CDC42." (PMID 24498060, 2014).
dyslipidemia (2 papers, 2023). "Moreover, curcumin, a lipophilic polyphenol derived from the spice turmeric, which reduces weight, leptin, and leptin levels in patients with metabolic syndrome and related disorders, can inhibit Cdc42 activity." (PMID 38068822, 2023).
E. coli infection (2 papers, 2021 to 2023). "In the pathogenic Escherichia coli infection and T cell receptor signaling pathway, we found that Cdc42 was up-regulated in all four groups." (PMID 37432027, 2023). "Expression of engulfment mediators MARCKS, RhoB, and CDC42 were reduced or unchanged following succinate or lactate treatment and increased in itaconate-treated macrophages following E. coli infection." (PMID 34350128, 2021).
embryonal carcinoma (2 papers, 2022 to 2025). A non-seminomatous malignant germ cell tumor characterized by the presence of large germ cells with abundant cytoplasm resembling epithelial cells, geographic necrosis, high mitotic activity, and pseudoglandular and pseudopapillary structures formation. "Indeed, we previously showed that CDC42 is involved in the cell fate determination of Nestin-positive neural progenitor cells by controlling the expression of tissue-specific transcription factors, using embryonal carcinoma P19 cells as a model system." (PMID 36206843, 2022). "As previously shown, the P19 embryonal carcinoma cell line that stably expresses Myc-CDC42 but not Myc-CDC42b failed to become neurons and upregulate the expression of MAP2 in RA-induced neuronal differentiation." (PMID 36206843, 2022).
epidermoid carcinoma (2 papers, 2003 to 2024). "In the A431 epidermoid carcinoma cell line, which is derived from human keratinocytes, Cdc42 activity partly corresponded to keratinocytes and fibroblasts, and was elevated both during cell protrusion and retraction phases." (PMID 37910204, 2024).
focal segmental glomerulosclerosis (2 papers, 2016 to 2021). A renal disorder characterized by sclerotic lesions in the glomeruli. "Using immunofluorescent staining, we also investigated the expression of Cdc42 in glomerular podocytes of patients with nephropathy (DN) or focal segmental glomerulosclerosis (FSGS)." (PMID 26986510, 2016).
gestational diabetes (2 papers, 2019 to 2020). Carbohydrate intolerance first diagnosed during pregnancy. "One study showed that up-regulation of miR-330-3p reduces expression of Cdc42 and E2F1 leading to impaired β cell proliferation via transferring from the plasma membrane to the cytoplasm of β cells in gestational diabetes mellitus (GDM)." (PMID 30621321, 2019). "One study showed that upregulation of miR-330-3p reduces the expression of CDC42 and E2F1 in patients with gestational diabetes (GDM), resulting in impaired β-cell proliferation." (PMID 33149760, 2020).
glaucoma (2 papers, 2021 to 2025). Increased pressure in the eyeball due to obstruction of the outflow of aqueous humor. "The specific activation of Cdc42 by the IL-8/CXCR2 pathway emphasizes its critical role in the pathophysiology of viral-induced glaucoma, offering potential avenues for therapeutic intervention." (PMID 40353220, 2025). "With respect to glaucoma, it was shown that CDC42 is responsible for maintaining the tight junction permeability in the trabecular meshwork and regulates its outflow resistance by cytoskeletal rearrangement." (PMID 34440217, 2021). "Specifically, targeting the IL-8/CXCR2/Cdc42 axis could provide a new approach to modulate TM cell motility and contraction leading to reducing outflow resistance and preventing the progression of glaucoma." (PMID 40353220, 2025).
HIV-1 infection (2 papers, 2017 to 2025). The type species of lentivirus and the etiologic agent of acquired immunodeficiency syndrome (AIDS). "Collectively, this study has reinforced the importance of the cytoskeleton in optimal HIV-1 infection of host cells and implicated RhoA, Cdc42, and ROCK as host dependency factors for viral replication." (PMID 28114951, 2017). "Interestingly, MDDCs transduced with shRNA targeting N-WASP (WASL), WIP (WASPIP) and CDC42 also exhibited increased susceptibility to HIV-1 infection." (PMID 40029073, 2025).
Hypertension (2 papers, 2015 to 2022). The presence of chronic increased pressure in the systemic arterial system. "Podosome formation in response to topography, wounding and hypertension studies was inhibited by a Src inhibitor or dominant negative cdc42." (PMID 25785437, 2015).
inflammatory bowel disease (2 papers, 2022 to 2026). A spectrum of small and large bowel inflammatory diseases of unknown etiology. "Moreover, CDC42 expression has been reported in inflammatory bowel disease (IBD)." (PMID 41511725, 2026).
inflammatory skin disease (2 papers, 2019 to 2025). Inflammatory skin disorders covers a broad category that includes many conditions ranging in severity, from mild itching to grave medical health complications These disorders are common in people of all ages and races. "In this context, we propose that a keratinocyte-specific Cdc42-deficient mouse model may be relevant to inflammatory skin disease." (PMID 31410202, 2019). "It is clear that while CASIN and other analogs that target CDC42 GTPases may have promising anti-aging properties, they would have little efficacy in preventing angiogenesis that is commonly observed in inherited and inflammatory skin disease." (PMID 40950721, 2025).
intestinal tumor (2 papers, 2017 to 2021). "Concordantly, another study has shown that the inhibition of CDC42 blocks the formation of intestinal tumors and it is highly expressed in intestinal tumor stem cells." (PMID 28460460, 2017). "In agreement with the role of CDC42 in cell migration and movement, overexpression of Cdc42 induced APCMin/+ intestinal tumor progression in mice; consequently, inhibiting CDC42 activity in β-catenin–mutant mice could lead to intestinal tumorigenesis suppression." (PMID 33406731, 2021). "Our results have been reinforced by recent studies showing that CDC42 activation promotes adhesion and invasion of CRC cells and that incipient intestinal tumor cells activate CDC42 as a crucial step in malignant progression." (PMID 28460460, 2017).
invasive breast ductal carcinomas (2 papers, 2013 to 2017). "CDC42 overexpression has been reported in several other malignancies, including invasive breast ductal carcinomas." (PMID 28451966, 2017).
kidney damage (2 papers, 2016 to 2022). "Nevertheless, modulation of Cdc42 activity and its regulatory pathways might serve as a therapeutic target to prevent a vicious cycle in which kidney damage and impaired insulin secretion interact with each other and ultimately lead to an aggravated outcome." (PMID 36034435, 2022). "We investigated the expression of Cdc42 in human nephropathy with proteinuria." (PMID 26986510, 2016).
leiomyoma (2 papers, 2018 to 2022). A well-circumscribed benign smooth muscle neoplasm characterized by the presence of spindle cells with cigar-shaped nuclei, interlacing fascicles, and a whorled pattern. "For example, genome-wide analysis revealed that the 1p36.12 region, where CDC42/WNT4 is located, was associated with uterine fibroids." (PMID 35903355, 2022). "Several studies reported that CDC42 might also play an essential role in the pathogenesis of fibroid." (PMID 35903355, 2022).
lung disease (2 papers, 2018 to 2022). "In particular, validation of a role for Cdc42 in primary bronchial epithelial cells, or whether the Cdc42 pathway is dysfunctional in primary cells from lung disease patients should be examined." (PMID 36618374, 2022). "We believe that endothelial cell CTGF-dependent interaction with Cdc42 in the recruitment of circulating CD11b+ myeloid cells is a singular example of a relevant protective pathway, possibly contributing to observed benefit in human clinical trials of anti-CTGF drugs related to pulmonary disease." (PMID 29535639, 2018).
lymph node metastases (2 papers, 2013 to 2022). "Enhanced immunoreactivity of all analysed proteins was found to be associated with the presence of lymph node metastases (ezrin, P = 0.047, moesin, P = 0.038, RhoA, P = 0.024, RhoB, P = 0.004 and Cdc42, P = 0.047)." (PMID 23420497, 2013). "In our study, over-expression of RhoA, RhoB and Cdc42 was found to be strongly associated with the presence of lymph node metastases." (PMID 23420497, 2013). "Of note, positive correlations between Rac/Cdc42 activity and lymphatic vessel invasion, venous invasion, and lymph node metastasis were detected." (PMID 35110666, 2022). "Rac/Cdc42 activity also seems to be positively associated with venous invasion and lymph node metastasis, although they were not statistically significant due to a likely insufficient number of samples to analyze." (PMID 35110666, 2022).